ACE (angiotensin I converting enzyme)
Diseases named in the same sentence as ACE in open-access papers (continued):
Sharing a sentence is not in itself a finding about the gene and the disease.
renal disease (continued). "D allele of ACE gene might confer a high risk of developing renal diseases and this association was highly compounded when D allele was present in homozygous state." (PMID 21859496, 2011). "63.7 % of patients achieved TD for ACE inhibitors, while 36.3 % received less than 50 % due to factors such as up-titration or renal disease." (PMID 41459384, 2026). "Clinical trials have demonstrated that only full-dose ACE inhibitors and ARBs effectively slow kidney disease progression, whereas subtherapeutic doses offer limited benefit." (PMID 40660221, 2025). "A 10-year follow-up of children receiving lisinopril, an ACE inhibitor, showed that early treatment reduced systolic blood pressure and proteinuria, particularly in children with renal disease." (PMID 40806733, 2025). "Current guidelines in the United States for managing patients with AS who are in stages 1–4 of kidney disease (with an eGFR) between 15 and 90+ mL/min/1.73 m2) emphasize the early initiation of treatment with ACE inhibitors or ARBs." (PMID 40165927, 2025). "A number of experimental studies have shown beneficial effects of angiotensin-converting enzyme (ACE) inhibitors in various models of advanced kidney disease, including 5/6 nephrectomy models with extensive removal of nephron mass." (PMID 36224286, 2023). "Clinical therapy for renal diseases usually uses angiotensin-converting enzyme inhibitor (ACEI) and Ang II receptor blockers (ARBs) to decrease ACE/Ang II activation and ameliorate disease development." (PMID 38203500, 2023). "Clinical trials have demonstrated that treatment with ACE inhibitors or ARB and more recently with SGLT2 inhibitors markedly reduces the risk of renal disease progression and CV complications in this population." (PMID 36719097, 2023). "Considering its deleterious contribution to cardiovascular and renal diseases, ACE inhibitors (ACEi) and Ang II receptor blockers (ARBs) have been developed and are very widely used in patients with hypertension, heart failure and chronic kidney disease." (PMID 33804075, 2021). "Interference with the RAS system through ACE inhibition is common in the treatment of kidney disease, resulting in the decrease of aldosterone levels." (PMID 33668632, 2021). "ACE inhibitors are used in the treatment of kidney diseases to limit hypertensive renal injury, with much interest surrounding the immunomodulatory activity of captopril." (PMID 33668632, 2021). "RAAS inhibitors, such as angiotensin-converting enzyme (ACE) inhibitors and angiotensin receptor blockers (ARBs), are considered as first-line treatments for hypertensive individuals with kidney disease." (PMID 35222012, 2021). "Drugs that can block the RAAS such as ACE inhibitors and angiotensin receptor blockers are able to provide nephroprotection and delay the progression of renal disease." (PMID 33460427, 2021). "In patients with renal disease leading to hypertensive crisis, the treatment often includes angiotensin-converting enzyme (ACE) inhibitors, beta blockers, and diuretics." (PMID 33194923, 2020). "Inhibition of ACE attenuates the decline in renal function and structural damages in kidney diseases." (PMID 32410988, 2020). "Clinical trials of angiotensin-converting enzyme (ACE) inhibitors and angiotensin II (Ang II) receptor blockers (ARBs) supported the experimental findings and were shown to retard the progression of renal disease." (PMID 32210089, 2020). "Currently, interruption of the RAAS with angiotensin-converting enzyme (ACE) inhibitors and angiotensin receptor blockers (ARBs) has become a leading strategy in slowing the progression of kidney disease." (PMID 30941188, 2019). "Information on the impact of salt intake on the course of heart and kidney disease isstill unclear but it indicates that the cornerstone for tissue inappropriateactivation of RAAS is the ACE/ACE2 ratio, leading to augmented local Ang II andAT1R activation." (PMID 29944159, 2018).
renal disease (continued). "Their limited efficacy in halting the progression of cardiovascular and renal diseases has been at least partly explained by an escape phenomenon, the synthesis of Ang II through alternative ACE independent enzymatic pathways." (PMID 30064425, 2018). "Since PPAR-γ is also associated with ACE, it is also useful to probe the effect of curcumin on the ACE expression in renal diseases." (PMID 28546962, 2017). "More than 40 million people worldwide are currently treated with angiotensin converting enzyme- (ACE-) inhibitors due to cardiovascular or renal disease." (PMID 27123347, 2016). "As ACE inhibitors are first choice in patients with cardiac or kidney diseases and such diseases are known to correlate with increased sPRR levels as well, the confounding factor is not distinct yet." (PMID 27660742, 2016). "Currently, most drugs used in clinical practice for renal disease, such as antioxidants, glucocorticoids, angiotensin converting enzyme (ACE) inhibitors and statins, both directly or indirectly inhibit NF-κB activation." (PMID 26194431, 2015). "If identified at an early stage, interventions like antiretroviral (ARVs) and angiotensin converting enzyme (ACE) inhibitors can be put in place to slow down or halt renal disease progression." (PMID 26161174, 2015). "ACE is the molecular target of an important class of drugs, the ACE inhibitors, widely used in the therapy of cardiovascular and renal diseases." (PMID 24639651, 2014). "The role of ACE inhibitors in reducing the decline rate of renal function in various kidney diseases is well documented." (PMID 24959534, 2013). "In various models of experimental renal disease, an attenuation of oxidative stress following ACE inhibitors(ACEI) or AT1R antagonist (ARB) administration has been demonstrated." (PMID 23658831, 2013). "In small studies, ARB and ACE inhibitor combinations were shown to be beneficial in patients with CV or renal disease, with improvement in surrogate markers." (PMID 23866091, 2013). "The elevated ACE expression increases the plasma angiotensin II level, and promotes podocyte injury which leads to progressive kidney diseases as well as DN." (PMID 24282791, 2013). "Blockade of AngII, by ACE inhibitors or receptor blockers, is one the current clinical therapies that have proven to ameliorate renal disease progression." (PMID 22792351, 2012). "The aim of the present study was to investigate the association between polymorphisms of the ACE and AT1RA1166C genes and the occurrence of renal disease in 76 advanced CKD (stages 4 and 5) pediatric patients undergoing MHD or CT." (PMID 21859496, 2011). "High BP does not appear to play the only role in the development of renal pathology since ACE inhibition controlled BP effectively in SHR but only postponed the onset of kidney disease." (PMID 21603136, 2011). "The first ACE inhibitor to be used in the clinic, captopril, showed dramatic beneficial effects in type I diabetic patients with nephropathy." (PMID 22126210, 2011). "The ACE I/D polymorphism is a useful test to predict the renoprotective effect of ACE inhibitor or angiotensin receptor blocker treatment in patients with kidney disease." (PMID 23049672, 2011). "Angiotensin-converting enzyme (ACE) inhibitors have a potential to slow down the progression of renal disease and therefore provide a renal-protective effect." (PMID 22022539, 2011). "Supporting these findings is the demonstrated ability of ACE inhibitors, ARBs, and aldosterone antagonists to delay renal disease progression in this model." (PMID 20678234, 2010). "Since the early 1990's reports have described reduced proteinuria and a "renoprotective" effect of angiotensin converting enzyme (ACE) inhibition and strict blood pressure control in renal disease in humans." (PMID 17480218, 2007).
renal disease (continued). "Proponents of ACE-inhibitors argue that hypertensive patients with kidney disease benefit both from the general antihypertensive effect of ACE-inhibitors and a specific 'kidney sparing' effect associated with this class of drugs." (PMID 15839739, 2005). "We conducted a systematic review to assess the effect modification of the insertion/deletion (I/D) polymorphism of the ACE gene on any outcome in patients treated with ACE inhibitors for cardiovascular and/or renal disease." (PMID 16242049, 2005). "ACE also regulates kidney function, and ACE inhibitors are commonly used to treat kidney disease." (PMID 40807208, 2025). "Current studies found that ACE inhibitors, angiotensin receptor blockers, anti-hypertensive agents, diuretics, insulin, and statins are potential risk factors for AKI or other kidney diseases." (PMID 37237361, 2023). "ACE inhibitors and type 1 ARBs may slow the progression of kidney disease by offering antiproteinuric effects." (PMID 35308174, 2022). "Moreover, further studies are needed to investigate the alterations in GFR and renal disease and the impact of ACE inhibitors on renal hemodynamics within this young obese population." (PMID 34975523, 2021). "At univariate analysis, as compared to the subjects with mild disease, those with severe or very severe/lethal disease were significantly more likely to be older, diabetics, hypertensive, diagnosed with COPD, CVD, and renal disease, and treated with ARBs and/or ACE inhibitors (all p<0.05)." (PMID 32579597, 2020). "Angiotensin II converted by ACE is a potent pro-inflammatory modulator for immune responses in the renal tissues and shows robust potential in mediating the development and progression of renal disease during SLE." (PMID 30618805, 2018). "Prevention or delay of ESRD-D involves control of blood pressure and blood glucose, early identification and monitoring of kidney disease, and use of angiotensin converting enzyme (ACE) inhibitors and angiotensin II receptor blockers (ARB) in patients with albuminuria." (PMID 28081061, 2017). "Indeed, ACE inhibitors have since become the mainstay of preventing the progression of renal disease in individuals with DN." (PMID 27935823, 2016). "Several models of kidney disease in both rodents and humans display local induction of the angiotensin converting enzyme (ACE) which is a well-known enzyme capable of forming Ang II from Ang I, providing an explanation for the elevated renal levels of Ang II in several pathological conditions." (PMID 25945342, 2015). "Taken together the data suggests that imbalance in the tissue RAS with upregulation of the deleterious ACE/Ang II pathway and loss of the protective ACE2/Ang 1–7 pathway may predispose to the development and progression of kidney disease." (PMID 25786223, 2015). "However, the antiproteinuric effect of ACE inhibitors on proteinuria is variable and the percentage of reducing proteinuria is in the range of 20–80% in a variety of renal diseases." (PMID 25587546, 2014). "For example, we have previously shown that genes involved in Pharm-GKB derived ACE-inhibitor pathway show altered multivariate gene expression patterns in the kidneys of patients with renal disease which is consistent with their levels of tubular atrophy/interstitial fibrosis." (PMID 23060897, 2012). "Following this study, several clinical trials demonstrated that ACE inhibition could significantly prevent the progression of renal disease." (PMID 22126210, 2011). "Similarly, recent clinical practice guidelines recommend ACE-inhibitors as the preferred first-line therapy for hypertensive patients with mild kidney disease." (PMID 15839739, 2005). "However, chymase hydrates Ang I to Ang II independently of ACE in some kidney diseases, and it may play an important role." (PMID 30633770, 2019). "The role of the ACE I/D polymorphism in non-diabetic renal disease is less well established." (PMID 23049672, 2011).
renal disease (continued). "Mild cases were treated with SGLT2-inhibitors such as JARDIANCE (empagliflozin) to reduce proteinuria, and ACE-inhibitors such as COVERSYL (perindopril) were administered to lower blood pressure and slow the progression of kidney disease." (PMID 39519211, 2024). "This typically involves the use of angiotensin-converting enzyme (ACE) inhibitors or angiotensin receptor blockers (ARBs), in line with the KDIGO (Kidney Disease: Improving Global Outcomes) guidelines." (PMID 39273032, 2024). "AT1R is expressed in a variety of kidney cells, including podocytes, and the activated ACE/Ang II/AT1R axis can induce vasoconstriction and multiple signal transduction pathways that lead to podocyte damage and renal disease." (PMID 37364145, 2023). "Once again, finerenone proved to reduce the risk of cardiovascular and kidney outcomes in diabetics on maximal dose ACE inhibitor or ARB, with lower rates of hyperkalemia compared to placebo across stages of kidney disease." (PMID 38105902, 2023). "Administration of ACE inhibitors or/and SGLT2 inhibitors show renoprotective effects in diabetic and other kidney diseases." (PMID 36171965, 2022). "It is well established that RAAS-inhibition via the angiotensin-converting enzyme (ACE) and angiotensinogen I (ATI) inhibitors alleviates the progression of many kidney diseases including radiation nephropathy." (PMID 34660640, 2021). "Clinical therapy for renal diseases generally includes angiotensin-converting enzyme inhibitor (ACEI) and Ang II receptor blockers (ARBs) to decrease ACE/Ang II activation and ameliorate disease development." (PMID 30633770, 2019). "Among RAAS candidate genes, angiotensinogen (AGT), angiotensin II type I receptor (AGTR1), angiotensin-converting enzyme (ACE), and aldosterone synthase (CYP11B2) genes appear to be particularly relevant to renal disease." (PMID 24977181, 2014). "Angiotensin-converting enzyme (ACE) and ACE2 are involved in several pathologies such as cardiovascular functions, renal disease and acute lung injury." (PMID 25391767, 2014). "Given that mechanistically, ACE inhibitors and ROCK inhibitors act on different pathways to prevent renal disease, we determined the impact of combined application of Ramipril and SAR407899 on albuminuria, the most sensitive parameter of glomerula dysfunction." (PMID 24244677, 2013). "Among the candidate genes of the RAS, the ACE, and angiotensin II type 1 receptor (AT1RA1166C) genes seem to be particularly biologically and clinically relevant to renal disease." (PMID 21859496, 2011). "Angiotensin converting enzyme (ACE) inhibitors have been widely used in the treatment of cardiovascular and renal diseases." (PMID 20180980, 2010). "Meanwhile, Kidney Disease: Improving Global Outcomes (KDIGO) guidelines stress individualized reno-protective strategies, including RAAS blockade (using ACE inhibitors or angiotensin receptor blockers) and SGLT2 inhibitors to reduce CKD progression and cardiovascular risk." (PMID 40227756, 2025). "Treatment with the highest tolerated dose of an ACE inhibitor (or an Angiotensin Receptor Blocker (ARB)) is often effective in delaying kidney disease but does not provide a cure." (PMID 38745975, 2024). "The nonspecific use of angiotensin-converting enzyme (ACE) inhibitors (ACEi) has been the gold-standard treatment to delay the progression of AS as well as other types of kidney diseases." (PMID 34793332, 2022). "Thus, blockade of RAS, including the use of angiotensin-converting enzyme (ACE) inhibitors or angiotensin II receptor blockers (ARB), can effectively suppress the progression of kidney diseases in both animal experiments and large-scale clinical studies." (PMID 32144368, 2020). "The three remaining RAAS genes included in this meta-analysis, ACE2, AGTR2 and REN, have not been researched as extensively as ACE, AGT and AGTR1 for associations with renal disease." (PMID 31048445, 2019).
renal disease (continued). "Therefore, current pharmacotherapeutic strategies have focused on inhibiting the production of Ang II (ACE inhibitors and direct renin inhibitors) or AT1R blockade [angiotensin receptor blockers (ARBs)] to delay the progression of renal diseases." (PMID 26556707, 2015). "Timely blockade with ACE inhibitors, renin inhibitors or AT1 receptor antagonists can promote reversal of renal lesions and ultimately prevent the evolution towards end-stage organ failure in experimental models of renal disease." (PMID 22403621, 2012). "However, antihypertensive therapy, especially with angiotensin-converting enzyme (ACE) inhibitors, are believed to influence positively the course of recurrent or de novo renal disease in the graft." (PMID 17955265, 2009). "Compared with ACE inhibitor as the reference treatment, no RAS blocker used in monotherapy and/or combination was associated with any significant reduction of progression of renal disease." (PMID 26954482, 2016). "But previous studies demonstrated that both ACE inhibitors and ARBs reduce ADMA levels in patients without kidney disease." (PMID 26494370, 2015). "However, blood pressure reduction with ACE inhibitors and AT1R antagonists still represents the first-line treatment for CKD patients, and could not fully prevent the progression of renal disease and CKD patients are still requiring more efficacious treatment options." (PMID 34550407, 2021).